ORAI1 (ORAI calcium release-activated calcium modulator 1)
Diseases named in the same sentence as ORAI1 in open-access papers (continued):
Sharing a sentence is not in itself a finding about the gene and the disease.
colon cancer (continued). "The interplay of SK3, a Ca2+ sensitive K+ ion channel, with Orai1, a Ca2+ ion channel, has been reported to increase cytosolic Ca2+ levels, thereby triggering proliferation of breast and colon cancer cells, although a molecular mechanism has remained elusive to date." (PMID 34944977, 2021). "Previous reports on breast and colon cancer cells reported extensively that their proliferation is driven by a co-regulation of co-localized Orai1 and SK3 channels, while the molecular determinants for this remained unknown." (PMID 34944977, 2021). "Whereas ORAI1 channels in normal cells are essentially inactivating, in colon cancer cells, perhaps the involvement of TRPC1 channels may contribute to sustain currents." (PMID 32733237, 2020). "This study demonstrates that the inhibition of the SOCE-dependent colon cancer cell migration trough SK3/TRPC1/Orai1 channel complex by the alkyl-lipid Ohmline may be a novel strategy to modulate Anti-EGFR mAb action in mCRC." (PMID 27102434, 2016). "We discovered that the interplay between Orai1 and SK3, similar to that in breast and colon cancer cells, also occurs in HEK 293 cells." (PMID 36612099, 2022). "It was recently reported that hypoxia could trigger the activation of NFATc3 via upregulation of Orai1, which leads to increased intracellular Ca2+ and the following activation of calcineurin, resulting in NFATc3 dephosphorylation and nuclear import in colon cancer cells." (PMID 35484132, 2022). "Specifically, breast and colon cancer progression has been demonstrated to be governed by the interplay of SK3 and Orai1." (PMID 36612099, 2022). "In particular, the co-regulation of the Orai1 and SK3 channels has been well-studied in breast and colon cancer cells, where it finally leads to an invasion-metastasis cascade." (PMID 36612099, 2022). "In contrast, SigmaR1 was directly bound to SK3 in breast and colon cancer cells and supported the interplay of SK3 and Orai1." (PMID 35327543, 2022). "In breast and colon cancer cells, this SK3/Orai1 interplay was shown to occur in cholesterol-rich regions." (PMID 35327543, 2022). "In colon cancer cells, SK3 has been reported to colocalize not only with Orai1, but also with TRPC1 channels in lipid rafts." (PMID 33333945, 2020). "They demonstrate that reducing the expression of TRPC1 inhibits migration of the HCT-116 colon cancer cell line by disrupting the complex formation of Ca2+-activated K+ channels (SK3), ORAI1, and TRPC1 in the lipid rafts." (PMID 32046188, 2020). "Another study further demonstrated that enhanced Orai1 and decreased STIM2 expression drive colon cancer cell development." (PMID 33333945, 2020). "In the colon cancer cell HCT-116 line, activation of STIM1 by Ca2+ store depletion, using TG, results in the recruitment of Orai1 and TRPC1 into lipid raft domains containing SK3 channels." (PMID 30558192, 2018). "Recently, human colon cancer cells have been shown to present an increase of SOCE, related to an increase in TRPC1, Orai1, Orai2, Orai3 and STIM1 expressions." (PMID 27102434, 2016). "Similarly, colon cancer cell growth is driven by an interplay of SK3 and Orai1 which is further supported by STIM1 and TRPC1." (PMID 35327543, 2022). "Same results were obtained in colon cancer cells by the same group of researchers, where potentiation of SOCE mediated by hypoxia-induced upregulation of ORAI1 determined the activation of NFATc3, enhancing hypoxia-induced invasion and angiogenesis in colon cancer cells." (PMID 35806388, 2022). "In contrast, in colon cancer cells, SOCE is mediated by both ORAI1 and TRPC1 channels." (PMID 32733237, 2020). "For example, in human colon cancer, a complex interplay between TRPC1/Orai1 and STIM2 was identified, with TRPC1/Orai1 expression upregulation being associated with increased SOCE and Ca2+ store content, whereas STIM2 downregulation underlying Ca2+ store depletion and promoting apoptosis resistance." (PMID 32872338, 2020).
colon cancer (continued). "For example, the EP4 receptor, the predominant PGE2 receptor subtype in HT-29 and HCA-7 human colon cancer cell lines, activates PI3K and induces Ca2+ influx from the extracellular space through Orai1, resulting in ERK phosphorylation and migration of oral cancer cells." (PMID 33511115, 2020). "However, in colon cancer cells, SOCE depends on both ORAI1 and TRPC1 channels as reviewed next." (PMID 32733237, 2020). "In fact, increased expression of molecular players involved in SOCE, particularly Orai1 and Stim1, may not be enough to sustain Ca2+ in colon cancer cells." (PMID 28903423, 2017). "Since we observed that STIM1 binding to Orai1 reduces the co-localization with SK3 in HEK293 cells, it might be interesting to determine whether and how endogenous as well as overexpressed STIM1 affect the co-localization and interplay of SK3 and Orai1 in colon cancer cells." (PMID 36612099, 2022). "Previous reports on breast and colon cancer cells revealed enhanced Ca2+ levels due to an interplay of SK3 and Orai1, independent of STIM1." (PMID 34944977, 2021). "Interestingly, SOCs in colon cancer cells, but not in normal cells, involve Na+ currents mediated by TRPC1 that form a channel complex with Orai1, thus allowing Na+ influx." (PMID 28903423, 2017).
melanoma (23 papers, 2014 to 2025). A malignant, usually aggressive tumor composed of atypical, neoplastic melanocytes. "Plateau phases in melanoma cells are produced by STIM1/ORAI1 store-operated Ca2+ entry and mechanosensitive TRPM7/TRPV4 channels, which transform perivascular forces and osmotic conditions into electrical signals." (PMID 41463339, 2025). "Melanoma cells express high levels of Orai1 and STIM2, both of which control store-operated Ca2+ entry." (PMID 39764412, 2024). "We first established models of human melanoma cells (SK-Mel-2, C8161 ad SK-Mel-24 cells) transduced with Orai1-targeting short hairpin RNA (shRNA) using lentivirus, and then we measured SOCE by Fluo-4AM fluorescence imaging of intracellular Ca2+ levels." (PMID 37759164, 2023). "They reported that Orai1 was expressed in dermal tumor nests and blood vessel infiltrates of melanoma patients, suggesting that Orai1 is a maker of highly invasive tumor cell types." (PMID 37759164, 2023). "Silencing of Orai1 decreased the numbers of metastatic colonies in the lungs of mice, suggesting that Orai1 regulates the metastasis of melanoma in vivo." (PMID 37759164, 2023). "The roles of UV radiation in melanoma with calcium signaling involvement occur mainly by influencing vitamin D signaling, mitochondria-related Ca2+ influx, and ORAI1 channel-mediated melanogenesis." (PMID 35162934, 2022). "High levels of STIM1, STIM2 and SOCE were also documented in metastatic melanoma as compared to primary melanoma and knockdown of Orai1 and/or STIM2 reduced melanoma cell migration and invasiveness." (PMID 34069353, 2021). "Mechanistically, STIM1/Orai1-mediated Ca2+ oscillations promoted the assembly of invadopodia precursors in melanoma cells by activating Src kinase." (PMID 31252656, 2019). "In human melanoma, STIM2 and Orai1 were highly expressed in primary human melanomas and elevated in the invasive rim of the lymph node metastatic tumors." (PMID 31252656, 2019). "For instance, ORAI1-mediated Ca2+ entry stimulated human melanoma cell migration by recruiting Ca2+/Calmodulin-dependent kinase II (CaMKII) to induce Raf-1 phosphorylation, thereby activating the ERK pathway." (PMID 30754672, 2019). "A recent study demonstrated that STIM1- and Orai1-mediated SOCE promotes melanoma invasion and ECM degradation by increasing invadopodia formation and activity." (PMID 28912430, 2017). "It was also demonstrated that Ca2+ oscillations initiated by STIM1 and ORAI1 regulated invadopodium formation and proteolysis in melanoma cells." (PMID 28596940, 2017). "In a recent study, VAL inhibited skin photoaging-related ion channels, TRPV1 and ORAI1, and UV-induced melanogenesis in melanoma cells." (PMID 27630735, 2016). "They found that STIM1 and ORAI1 were expressed at high levels in human melanomas and melanoma cell lines." (PMID 25710007, 2015). "Ca2+ peak amplitude in the SOCE phase was lower in both STIM1- and Orai1- knockdown cells than in control metastatic melanoma cell lines." (PMID 24586666, 2014). "Western blot analyses showed that STIM1 and Orai1 are expressed in metastatic human melanoma cell lines, while the melanocyte cell line, HEMA-LP, displayed only a low level of Orai1 expression." (PMID 24586666, 2014). "We found that STIM1 and Orai1 isoforms were abundantly expressed in human melanoma tissues and multiple melanoma/melanocyte cell lines." (PMID 24586666, 2014). "Our data demonstrate that STIM1 and Orai1 have roles in proliferation and migration of various melanoma cell lines, indicating that SOCE contributes to melanoma progression." (PMID 24586666, 2014). "STIM1 and Orai1 were expressed not only in cultured melanoma cells, but also in human melanoma tissues." (PMID 24586666, 2014). "Melanoma cell growth and invasion are inversely controlled by Orai1 and STIM2 in a dynamic manner." (PMID 39764412, 2024). "Taken together, Orai1 plays important roles in melanoma cell proliferation and migration." (PMID 37759164, 2023).
melanoma (continued). "We established human melanoma cells transduced with Orai1-targeting shRNA using lentivirus." (PMID 37759164, 2023). "We also examined the expression of Orai1 in human melanoma tissues by a microarray." (PMID 37759164, 2023). "We previously demonstrated that the transduction of Orai1-targeting shRNA into human melanoma cells (SK-Mel-2 and SK-Mel-24 cells) using lentivirus decreased cell migration according to boyden chamber assays as well as migration distance according to time-lapse video recording." (PMID 37759164, 2023). "We previously found that Orai1 plays important roles in cell apoptosis and migration in melanoma." (PMID 37759164, 2023). "Similarly, the PKC-dependent modulation of Orai1 activity has been reported in invasive melanoma cells and in rat basophilic leukaemia cells." (PMID 35884372, 2022). "A pro-migratory role of STIM2/Orai1-mediated SOCE has also been reported in melanoma." (PMID 31252656, 2019). "While changes in the expression and function of STIM1 and Orai1 have been found in a range of cancer types and thus implicated in disease progression, levels of STIM1 and Orai1 were not different between malignant and non-malignant melanoma cells." (PMID 29568366, 2018). "We also examined expression of STIM1 and Orai1 in human melanoma tissues, using a microarray." (PMID 24586666, 2014). "Therefore, we investigated whether Orai1 also plays an important role in SOCE in human melanoma cells." (PMID 37759164, 2023). "Indeed, knockdown of STIM1 and Orai1 reduced the migration of melanoma cells." (PMID 33333945, 2020). "In most cancer types, including breast, gastric, glioblastoma, melanoma, and renal cancer, migration and metastasis have been identified to be controlled by both STIM1 and Orai1." (PMID 36612099, 2022). "In melanoma cells, STIM1- and Orai1-dependent regulation of proliferation occurs through the CaMKII/Raf-1/ERK signaling pathway." (PMID 36612099, 2022). "In melanoma cells, the SOC channel Orai1 localizes to invadopodia and spontaneously mediates discrete Ca2+ transients." (PMID 36158191, 2022). "Downregulation of TPC2 expression in metastatic melanoma leads to a decrease of Orai1 expression and an increase of YAP/TAZ activity, which is responsible for melanoma’s aggressive property." (PMID 35162934, 2022). "The importance of Ca2+ flux in regulating melanoma proliferation and cell migration was previously suggested by experiments including a knockdown of STIM1 or Orai1 in human melanoma cell lines as well as a pharmacological inhibitor of SOCE." (PMID 29568366, 2018). "High levels of store-operated Ca2+ channel (ORAI calcium release-activated calcium modulator 1; ORAI1) and stromal interacting molecules 1 and 2 (STIM1 and 2) were described in melanoma cell lines and melanoma tissues." (PMID 28596940, 2017). "SOCE activity in melanoma cells was dependent on STIM1 and Orai1, and was reduced by SOCE inhibitor YM58483." (PMID 24586666, 2014). "Notably, among pyrazoles, BTP2/Pyr2 and Pyr3 can block Orai1, TRPC3, and STIM1 and inhibit melanoma." (PMID 36612099, 2022). "Orai1- and STIM1-mediated Ca2+ oscillations regulate melanoma ECM degradation by MT1-MMP." (PMID 35162934, 2022). "In melanoma cells, STIM1 and Orai1 have been reported to play a role in migration." (PMID 33333945, 2020). "A role for STIM1 and Orai1-mediated Ca2+ oscillations was further demonstrated in the context of cell invadopodium assembly and extracellular matrix (ECM) degradation in models of melanoma metastasis." (PMID 27417567, 2016). "Since STIM1 and Orai1 were detected in human melanoma tissues, we examined whether SOCE occurs in melanoma cell lines." (PMID 24586666, 2014). "In contrast, Orai1-knockdown inhibited proliferation in C8161 cells but not in SK-Mel-2 or SK-Mel-24 cells, suggesting that STIM1, rather than Orai1, is the key determinant of melanoma proliferation." (PMID 24586666, 2014).
melanoma (continued). "Valencene has been found to be an antagonist of the calcium ion channel TRPV1 and the slow release calcium release-activated calcium channel protein 1 (ORAI1), which inhibited the melanin content in UVB exposed melanoma cells, and may therefore be useful for treating photo-aging of the skin." (PMID 36551898, 2022). "However, another study showed lower levels of SOCE in invasive patient-derived melanomas compared to non-invasive melanoma and this downregulation appears to be due to PKC-dependent phosphorylation of Orai1, arguing for a complex relationship between SOCE and melanoma progression." (PMID 34069353, 2021). "Finally, overexpression of STIM1 and Orai1 failed to restore SOCE in any of the Wnt5a-expressing invasive melanoma cell lines examined." (PMID 27417567, 2016). "Notably, unlike the melanoma lines characterized in, STIM1 and Orai1 were found to be highly expressed in melanoma, but no expression of their homologs was observed." (PMID 27417567, 2016). "We examined whether SOCE in melanoma cell lines is regulated by STIM1 and Orai1." (PMID 24586666, 2014). "Interestingly, STIM1, but not Orai1, showed higher expression in metastatic melanoma than in primary melanoma." (PMID 24586666, 2014). "Indeed, we found that Orai1 was abundantly expressed in human primary melanoma cell lines (WM115 and WM1552 cells), human metastatic melanoma cell lines (SK-Mel-2, C8161, SK- and Mel-24 cells), a human melanocyte cell line (HEMA-LP cells) and a mouse melanoma cell line (B16 cells)." (PMID 37759164, 2023).
severe combined immunodeficiency (22 papers, 2012 to 2025). Severe combined immunodeficiency (SCID) comprises a group of rare monogenic primary immunodeficiency disorders characterized by a lack of functional peripheral T lymphocytes resulting in early-onset severe respiratory infections and failure to thrive. "Biallelic loss of Orai1 causes severe combined immunodeficiency (SCID) presenting with recurrent infections and autoimmunity from a few weeks of birth." (PMID 39796238, 2025). "Proper ORAI1 function is essential for immunity in humans and patients with ORAI1 mutations suffer from severe combined immunodeficiency." (PMID 34913437, 2021). "Mutations in the Orai1 or STIM1 genes abolish SOCE leading to combined immunodeficiency (CID), muscular hypotonia, and anhidrotic ectodermal dysplasia." (PMID 33650027, 2021). "Humans with Orai1 mutations also suffer from severe combined immunodeficiency (SCID)." (PMID 34248635, 2021). "Recessive STIM1 and ORAI1 loss-of-function (LoF) mutations resulting in insufficient SOCE cause CRAC channelopathies characterized by severe combined immunodeficiency (SCID) involving recurrent and chronic infections, autoimmunity, muscular hypotonia, ectodermal dysplasia, anhidrosis, and mydriasis." (PMID 33250786, 2020). "Orai1 channel activity is crucial for immune function, as human mutations in Orai1 result in severe combined immunodeficiency (SCID)." (PMID 29239723, 2017). "Loss of functional ORAI1 or STIM1 in humans leads to severe combined immunodeficiency (SCID)." (PMID 26052328, 2015). "Mutations in the genes encoding for Stim1 and Orai1 have long been associated to the development of rare, but lethal, inherited immunodeficiency disorders, such as severe combined immunodeficiency (SCID), where the abrogation of SOCE compromises immune system functions." (PMID 24603752, 2014). "A tryptophan mutation at this position causes the severe combined immunodeficiency (SCID) disease and completely abrogates Orai1 channel activity." (PMID 22802126, 2012). "Both Orai1 and STIM1 are critical for T cell immunity as evident from loss of function mutations of Orai1 or STIM1 which eliminate SOCE and result in impaired cytokine production, abrogated T cell activation, and severe combined immunodeficiency in patients." (PMID 36467682, 2022). "Moreover, loss of ORAI1 in T cells results in severe combined immunodeficiency (SCID), limiting the potential use of ORAI1 blockers as anti-thrombotics." (PMID 33600275, 2021). "Similarly, mutations in the gene encoding the Ca2+ release-activated Ca2+ (CRAC) channel, ORAI1, and its activator stromal interaction molecule 1 (STIM1), are implicated in severe combined immunodeficiency (SCID), tubular aggregate myopathy (TAM), and Stormorken syndrome." (PMID 40103710, 2025). "Feske and coworkers linked their findings in Drosophila to a region of human chromosome 12, containing the human homolog of dOrai1, Orai1 (also termed CRACM1), by the genetic mapping of members of a family that presented severe combined immunodeficiency (SCID)." (PMID 36498894, 2022). "Homozygosity for a missense mutation in Orai1, replacement of arginine with tryptophan at position 91 of the protein, abolishes the CRAC channel flow in T cells from patients with severe combined immunodeficiency (SCID)." (PMID 32210952, 2020).